KRT222 (keratin 222)
Synonyms: KA21; KRT222P; MGC45562
Tractability: No criterion of Open Targets' tractability assessment is met for any kind of drug.
Gene: Protein-coding gene on chromosome 17 (40,654,665 to 40,665,181, reverse strand). Ensembl gene ENSG00000213424.
Subcellular location (Human Protein Atlas): Lipid droplets; Vesicles
Gene Ontology:
Molecular function: protein binding; structural molecule activity
Genetic constraint (gnomAD): Loss-of-function variants: 16 observed, 30.65 expected, observed/expected ratio (o/e) 0.52, 90% interval 0.35 to 0.79. The upper end of that interval is the gene's LOEUF score, 0.79, which puts it in group 3 of 6, group 1 being the genes least tolerant of losing a copy. Missense variants: 307 observed, 323.74 expected, observed/expected ratio (o/e) 0.95, 90% interval 0.86 to 1.04. Synonymous variants: 99 observed, 113.46 expected, observed/expected ratio (o/e) 0.87, 90% interval 0.74 to 1.03.
Homologues: Orthologues: chimpanzee KRT222 (99% identical), macaque KRT222 (98% identical), pig KRT222 (96% identical), dog KRT222 (95% identical), mouse Krt222 (88% identical), rat Krt222 (87% identical), rabbit KRT222 (87% identical), guinea pig KRT222 (81% identical), tropical clawed frog krt222 (54% identical), zebrafish krt222 (45% identical). Paralogues in human: KRT27 (23% identical), KRT17 (22% identical), KRT24 (22% identical), KRT26 (22% identical), KRT14 (22% identical), KRT15 (22% identical), KRT12 (22% identical), KRT25 (22% identical), LMNA (22% identical), KRT10 (21% identical), KRT18 (21% identical), KRT20 (21% identical), and 56 more.
Diseases named in the same sentence as KRT222 in open-access papers:
KRT222 is named in the same sentence as 5 diseases in open-access papers, as found by Europe PMC text mining. Sharing a sentence is not in itself a finding about the gene and the disease. The quoted sentences say what the papers report.
glioma (2 papers, 2017 to 2023). A benign or malignant brain and spinal cord tumor that arises from glial cells (astrocytes, oligodendrocytes, ependymal cells). "Of note, KRT222, which was first detected in Gallus gallus, was down-regulated specifically in brain neoplasms (lower grade glioma and glioblastoma multiforme)." (PMID 36949761, 2023). "FSTL5, HCN1, TMEM132D, TRHDE and KRT222 showed the strongest expression correlation with other genes in the co-expression network of glioma tissues." (PMID 29046615, 2017).
cancer (2 papers, 2021 to 2023). A tumor composed of atypical neoplastic, often pleomorphic cells that invade other tissues. "Several members of the KRT gene family, including the evolutionarily older KRT8, KRT18, KRT19, KRT23, KRT79, KRT80 and KRT222, were shown to be differentially regulated in diverse cancer types." (PMID 36949761, 2023). "Several KRT genes, including the phylogenetically older KRT8, KRT18, KRT19, KRT23, KRT79, KRT80 and KRT222, were found to be differentially expressed in diverse types of cancers." (PMID 36949761, 2023).
tumor (1 paper, 2019). "The common prognostic genes between AS event and genes included KRT222, LENG8, APOB, SLC3A1, SCD5, AQP1, and ADRA1A, which played roles in tumor biology." (PMID 31140607, 2019).
KRT222 also shares sentences with these, for which no sentence is quoted: brain neoplasm (1 paper); glioblastoma multiforme (1).